ALB (albumin)
Diseases named in the same sentence as ALB in open-access papers (continued):
Sharing a sentence is not in itself a finding about the gene and the disease.
Pleural effusion (continued). "The patients had uneventful recovery except for one patient who had right pleural effusion and abdominal ascites that had to be drained and treated with medical therapy as diuretics and albumin." (PMID 26971195, 2016). "All 17 patients had plasma leakage and 8 (47.0%) had clinical fluid accumulation, manifested as pleural effusion (5 [62.5%] patients) and serum albumin <3.5 g/dL (5 [62.5%] patients)." (PMID 27196051, 2016). "The study showed that poor PS, low serum albumin level, pleural effusion, and bone and liver metastases were adverse prognostic factors." (PMID 26622812, 2015). "Unlike previous studies, we observed that compared to younger patients, older patients presented with more severe clinical findings such as lower serum albumin levels, leg edema, and pleural effusion." (PMID 25330372, 2014). "Although the exact physiopathological mechanisms of the development of pleural effusions in patients with C. difficile are not clearly understood, protein-losing enteropathy due to inflammation of the bowel wall and leakage of albumin into the colonic lumen is a potential mechanism." (PMID 39958076, 2025). "We evaluated the association of affordable lab works, such as C-reactive protein (CRP), procalcitonin, ferritin, neutrophil and lymphocyte counts, D-dimers, and albumin levels, with the extents of lung injury, pleural effusion, pulmonary embolism, and thoracic adenopathy." (PMID 40428888, 2025). "An albumin level of <35 g/L showed a significant impact on pleural effusion development." (PMID 39768615, 2024). "While a large amount of pleural effusion (800–1200 mL per day) was drained daily for nearly 4 months, serum total protein and albumin were not reduced, indicating no obvious loss of protein." (PMID 39061098, 2024). "Additionally, the serum-pleural effusion albumin gap before and after TIPS was differed (13.1 g/L vs. 6.4 g/L)." (PMID 39109224, 2024). "This study hypothesized that adding 100 mL of 20% human albumin to the CPB priming solution could reduce early postoperative pleural effusion development." (PMID 39768615, 2024). "Another possible explanations of the right-sided pleural effusion in our patient could be the rapid decrease in albumin." (PMID 36869391, 2023). "LR identified the following four independent variables as predictive of SAP: albumin (OR 0.88, 95%CI 0.81-0.95, P=0.002), serum creatinine (OR 1.02, 95%CI 1.01-1.03, P=0.002), glucose (OR 1.15, 95%CI 1.07-1.24, P<0.001), and pleural effusion (OR 5.11, 95%CI 2.38-10.94, P<0.001)." (PMID 35755843, 2022). "An additional study has reported that Sivelestat reduces the content of pleural effusion as well as levels of albumin (a marker of lung permeability), decreases myeloperoxidase activity (indicating neutrophil infiltration), amplifies oxygenation, and improves the survival rate." (PMID 34869231, 2021). "The multivariate analysis between OS and the variables selected from the univariate analysis showed that the levels of neutrophil, alkaline phosphatase, neuron-specific enolase, platelets, albumin in peripheral blood, and white blood cells in pleural effusion were also independent predictors of OS." (PMID 35083140, 2021). "Symptom duration, pulse rate, pleural effusion, pericardial thickness, albumin and serum sodium were not statistically associated with postoperative complication." (PMID 32560663, 2020). "Patients with high SABP scores may have much more pronounced risk factors, such as SIRS, pleural effusion, elevated BUN levels and low albumin, enhancing the risk of developing SAP." (PMID 31068202, 2019). "Furthermore, despite the emphasis on the importance of donor safety, few reports have assessed the impact of early postoperative albumin level on the development of pleural effusion in previously healthy liver donors." (PMID 30808903, 2019).
Pleural effusion (continued). "In addition, we found out that the prevalence of postoperative pleural effusion was lower in the donors infused with albumin solution, compared to those infused with synthetic colloid during donor hepatectomy." (PMID 30808903, 2019). "We also found that intraoperative use of albumin solution (from 2013 to 2014) resulted in significantly higher postoperative albumin levels and reduced incidence of postoperative pleural effusion than synthetic colloid use (from 2010 to 2012), before and after PS matching." (PMID 30808903, 2019). "A few previous research has reported other values of prognosis for PLA, which included older age, increased serum creatinine and BUN, low hemoglobin and albumin levels, biliary origin’s liver abscess, polymicrobial infection, pleural effusion, concomitant malignancy, and multiple abscesses." (PMID 30651062, 2019). "Therefore, further studies are warranted to determine the effect of albumin solution on postoperative pleural effusion." (PMID 30808903, 2019). "Certain conditions may decrease serum albumin levels such as pleural effusion, ascites, edema, or nephrosis." (PMID 30423847, 2018). "Moreover, VWF propeptide levels correlated better with markers of disease severity (platelet count, liver enzymes, serum albumin and pleural effusion index) than corresponding VWF levels." (PMID 22563509, 2012). "Patients with MV may also have transudative pleural effusion due to low serum albumin." (PMID 38875392, 2024). "Notably, albumin levels were lower in patients presenting with pleural effusions." (PMID 32914241, 2021). "This examination of albumin levels and the occurrence of pleural effusion after hepatectomy revealed that the lowest albumin level within POD 2 (POD2ALB) is an early and clinically relevant parameter to assess the association with the development of pleural effusion." (PMID 30808903, 2019). "Compared with younger patients, older patients had lower serum albumin levels (P = 0.014), lower eGFRs (P<0.001), higher serum creatinine levels (P = 0.011), higher systolic blood pressure (P = 0.028), and a higher prevalence of leg edema and pleural effusion (P = 0.020 and P = 0.048, respectively)." (PMID 25330372, 2014). "Patients with pleural effusion had significantly lower GFR (54.40 ± 20.21 vs. 62.29 ± 17.25 mL/min; p < 0.001) and albumin levels (33.94 ± 5.01 vs. 36.76 ± 6.52 g/dL; p = 0.037)." (PMID 40095579, 2025). "After controlling for the effect of the covariates (albumin and COP before surgery), we found a significant difference in the reduction in pleural effusion development after albumin infusion." (PMID 39768615, 2024). "Our study suggests a link between albumin addition to CPB priming solution and the reduction in early pleural effusion development." (PMID 39768615, 2024). "After controlling for the effect of the covariates (albumin and COP before surgery), we found significantly smaller pleural effusion volume in the albumin group." (PMID 39768615, 2024). "One of the most common secondary adverse events observed in this study was pleural effusion, leading to ICU or hospital readmission, with rates of occurrence being (7 [1.0%] in the albumin group and 9 [1.3%]) in the Ringer group." (PMID 39768615, 2024). "After adjusting for potential confounding variables (age, sex, body mass index, comorbidity, albumin, ejection fraction, c-reactive protein, RRF, and Total Kt/Vure), the overall mortality in pleural effusion raised significantly with HR 3.06 (2.36–3.96)." (PMID 38241413, 2024). "Our primary objective was to evaluate the effectiveness of adding 100 mL of 20% human albumin to the CPB priming solution compared to standard priming, with a specific focus on its potential role in reducing the occurrence of pleural effusion." (PMID 39768615, 2024).
Pleural effusion (continued). "Additionally, death (PT: 10,011,906), dyspnoea (PT: 10,013,968), pleural effusion (PT: 10,035,598), blood albumin decreased (PT: 10,005,287), haemoptysis (PT: 10,018,964), and central nervous system lesion (PT: 10,051,290), might cause by the disease progression." (PMID 38762672, 2024). "The same 16 variables (SIRS, hematocrit, platelets, prothrombin time, albumin, AST, glucose, serum creatinine, BUN, cholesterol, HDL, LDL, triglyceride, serum calcium, C-reactive protein, and pleural effusion) were used for the RF model." (PMID 35755843, 2022). "More ICU inpatients had dyspnea, lung moist rales, and pleural effusion; significantly higher respiratory rate, heart rate, LDH, BUN, CRP, and CAR; and significantly lower lymphocyte, albumin, and CD8+ T lymphocyte counts (all P < 0.05)." (PMID 36424963, 2022). "In previous studies, many factors have been reported as independent risk factors for the development of OF in AP, such as lipase, albumin, BUN, and pleural effusion." (PMID 34545276, 2021). "For the clinical features, fever, pleural effusion, high white blood cell count and CRP, and low level of serum albumin were more frequently seen in patients with advanced CKD than in those with early CKD." (PMID 32349734, 2020). "The bootstrap analysis revealed that, out of twelve potential predictors, SIRS, albumin, BUN and pleural effusion were reproducibly selected in more than 90%." (PMID 31068202, 2019). "However, due to the retrospective design of the study, we could not confirm the causal relationship between albumin administration and reduction of the incidence of postoperative pleural effusion." (PMID 30808903, 2019). "Univariate analysis identified death related biomarkers, mainly including MIF levels, age, cavitary lesion, pleural effusion, drug-resistant, disseminated status and CRP, IL-6 and ALB." (PMID 30841876, 2019). "Age, BMI, alcohol etiology, SIRS, hematocrit, platelet count, prothrombin time, albumin, AST, glucose, BUN and pleural effusion were identified as candidate predictors (P < 0.20) of SAP in univariate analysis." (PMID 31068202, 2019). "An intraperitoneal injection of 99mTc human serum albumin or 99mTc sulfur colloid should be carried out if the diagnosis of HH is uncertain, particularly when the pleural effusion is left-sided and/or ascites is not present." (PMID 40041630, 2025). "The exact mechanism of pleural effusion-related CDI is not clearly understood, but inflammation of the bowel wall, leakage of albumin into the colonic lumen, and increased vascular permeability due to toxin-induced cytokines are believed to play a role in the pathogenesis." (PMID 39958076, 2025). "Low albumin and COP levels may induce pleural effusion development, which could potentially become clinically significant, necessary to drain, and affect the postoperative period after the first day." (PMID 39768615, 2024). "In contrast, platelet counts; serum albumin, aspartate transaminase (AST), and alanine transaminase (ALT) levels; plasma leakage, including pleural effusion, ascites, or hemoconcentration; and secondary infection rates differed significantly between patients with DHF and DF." (PMID 38791534, 2024). "After applying LASSO analysis, 13 of the 29 candidate clinical parameters were further screened; 25(OH)D, length of symptoms, WBC count, D dimer, CRP, ferritin, albumin, mechanical ventilation, IL-8, ALT, pleural effusion, polylobular infection, and MP DNA copies." (PMID 36778550, 2023). "Except the LENT score, modified LENT score, SELECT model and PROMISE score items, we also found that serum albumin, serum and pleural effusion VEGF, pleural effusion PH, pleural effusion glucose and pleural effusion survivin are also valuable prognostic factors for malignant patients." (PMID 35209915, 2022).
Pleural effusion (continued). "These indicators include the clinical parameters such as ECOG PS, non-adenocarcinoma histology, EGFR mutation and LENT score, the serum indicators such as NLR, hemoglobin, total protein, albumin, LDH, CRP and VEGF, and the pleural effusion indicators such as PH, glucose, LDH, VEGF and surviving." (PMID 35209915, 2022). "Compared with early CKD, advanced CKD was associated with significantly higher rates of disseminated cryptococcosis and nonrecovery after treatment and more frequent clinical features of fever, pleural effusion, high white blood cell count and CRP, and low level of serum albumin." (PMID 32349734, 2020). "We denoted it as the SABP (SIRS, albumin, BUN and pleural effusion) score." (PMID 31068202, 2019). "Our findings suggest that patients with pleural effusion exhibited a more pronounced inflammatory response, alterations in coagulation parameters, and reduced protein and albumin levels, highlighting the severity and complexity of their condition compared to those without pleural effusion." (PMID 40428888, 2025). "However, patients with ATTR and pleural effusions had significantly lower serum albumin levels compared to patients without pleural effusions." (PMID 32914241, 2021). "According to many previous studies, PLA has many other prognostic values, such as older age, low level of albumin, and hemoglobin, increased BUN and serum creatinine, polymicrobial infection, biliary liver abscesses, multiple abscesses, concomitant malignancy, and pleural effusions." (PMID 31447784, 2019). "Moreover, pleural effusion in the patient in our report was completely cured by one cycle of VAD chemotherapy with no change in serum-albumin levels and cardiac and renal function." (PMID 20955545, 2010). "The covariates (albumin and COP before surgery) were not significantly related to pleural effusion, p > 0.05." (PMID 39768615, 2024). "However, in that study, there were important differences in population characteristics between patients with and without pleural effusion, including age, APACHE II scores, and albumin levels." (PMID 39634683, 2024). "Also, the covariates beforehand (albumin and COP before surgery) were not significantly related to pleural effusion, although an SAL of < 35 g/L significantly impacted the development of pleural effusion following CPB." (PMID 39768615, 2024). "An infusion of albumin before starting MTX also seems tempting but may not be recommended because of cost and side effects and probably should be reserved for children with edema, pleural effusion, or ascites." (PMID 39305296, 2024).
ischemia (136 papers, 2005 to 2026). A hypoperfusion of the BLOOD through an organ or tissue caused by a PATHOLOGIC CONSTRICTION or obstruction of its BLOOD VESSELS, or an absence of BLOOD CIRCULATION. "Our univariate analyses showed that low levels of albumin were associated with the presence of ischemia in MPS, as has been found in similar studies evaluating CAR and NPS." (PMID 40506944, 2025). "Albumin boosts patients’ immunity and tissue healing ability, minimizes brain tissue damage from ischemia, protects the oral mucosa, and lowers the risk of mouth dryness and infection." (PMID 41450526, 2025). "Another study investigated the implementation of standard operating procedures for the care of patients with TBI, whereas another study investigated risk prediction using ischemia-modified serum albumin." (PMID 39336939, 2024). "In the SHapley Additive exPlanation summary plot, medical treatment, type A acute aortic dissection, and higher ischemia-modified albumin level were shown to increase the risk of hospital-based mortality." (PMID 34604356, 2021). "Ischemia-modified albumin (IMA), a modification of human serum albumin caused by ischemia, measured by the albumin cobalt test has been proposed as a serum biomarker of myocardial ischemia." (PMID 27437482, 2014). "Under acute ischemic conditions, the metal binding capacity of albumin to transition metals such as copper, nickel and cobalt is reduced, generating a metabolic variant of the protein generally referred to as ischemia modified albumin (IMA)." (PMID 18513410, 2008). "Albumin could ameliorate inadequate skin blood flow caused by peripheral artery occlusion, modulate vascular permeability, lessen exudation, and relieve ischemia in diabetic foot." (PMID 39927281, 2025). "Therefore, ischemia-affected areas were identified by FITC-albumin extravasations indicative of an ischemia-associated BBB breakdown." (PMID 33931805, 2021). "In our study, low albumin levels were associated with ischemia." (PMID 33094574, 2020). "Reperfusion after ischemic conditions includes more free radical and iron and copper exposure, which may cause even more alterations to albumin than ischemia itself." (PMID 22221979, 2012). "Background and Objectives: Ischemia-modified albumin (IMA) has previously been identified as a biomarker for early ischemia, rapidly formed by acidosis and free radical modification of the N-terminus of human serum albumin." (PMID 42195204, 2026). "Our results extend this perspective by demonstrating that the NPS—which integrates albumin, total cholesterol, NLR, and LMR values—provides an even stronger association with ischemia." (PMID 40506944, 2025). "In summary, this study demonstrated that young women engaged in regular structured exercise exhibit significantly higher serum ischemia-modified albumin (IMA) concentrations and markedly lower total sulfhydryl (–SH) levels compared with their sedentary peers." (PMID 41357165, 2025). "EPR spectroscopy offers high specificity in detecting changes to albumin’s transport function and binding properties due to ischemia-induced oxidative stress, making it a highly informative research tool." (PMID 39407566, 2024). "Ischemia-modified albumin (IMA) is an albumin with a decreased affinity for cobalt ions resulting from ischemia and the production of reactive oxygen species." (PMID 39061994, 2024). "The increased adjusted ischemia–modified albumin levels were identified as predictors of the presence and severity of PAD." (PMID 38405142, 2024). "They reported that the TOS, OI, and ischemia modified albumin values were significantly lower in the HA groups compared with the control group." (PMID 38812617, 2024). "IMA is created from the alteration of albumin, induced by reactive oxygen radicals generated as a consequence of ischemia." (PMID 39925729, 2024). "When ischemia develops, free oxygen radicals emerge in the environment and damage the N terminus of albumin." (PMID 38141595, 2023).